CD4 (CD4 molecule)
Diseases named in the same sentence as CD4 in open-access papers (continued):
Sharing a sentence is not in itself a finding about the gene and the disease.
head and neck squamous cell carcinoma (66 papers, 2015 to 2026). A squamous cell carcinoma that arises from any of the following anatomic sites: lip and oral cavity, nasal cavity, paranasal sinuses, pharynx, larynx, and salivary glands. "A previous study showed that tumor-infiltrating activated CD4+ T cells are associated with a good prognosis in head and neck squamous cell carcinoma." (PMID 35711924, 2022). "On the contrary, high levels of tumor-infiltrating CD4+CD69+ T cells are associated with good prognosis in head and neck squamous cell carcinoma." (PMID 31649887, 2019). "Moreover, intratumoral CD4+ T follicular helper (TFH) cells were reported to enrich in HPV+ head and neck squamous cell carcinoma (HNSCC) and associate with longer progression-free survival." (PMID 33329692, 2020). "A study showed that patients with head and neck squamous cell carcinoma (HNSCC) with increased COL3A1 levels also had a higher level of resting CD4 + T cells and resting NK cells." (PMID 37415178, 2023). "According to the prognostic model of EC and head and neck squamous cell carcinoma (HNSCC) established by other researchers, tumors in high-risk patients were characterized by a higher proportion of CD4+ memory resting T lymphocytes." (PMID 36588538, 2022). "METTL3 and HNRNPC positively regulate CD4 memory-activated T cells and eosinophils in head-and-neck squamous cell carcinoma (HNSCC)." (PMID 35794625, 2022). "High expression of LINC02195 is positively correlated with an increased number of CD8+ and CD4+ T cells in the tumor microenvironment, proffering a favorable prognosis in patients with head and neck squamous cell carcinoma." (PMID 36425941, 2022). "In head and neck squamous cell carcinoma, LAMC2 expression was strongly associated with B cell, CD8+ T cell, CD4+ T cell, and macrophage infiltration levels." (PMID 34512203, 2021). "A study in head and neck squamous cell carcinomas found that Tregs represent only 2 to 15% of CD4+ TILs." (PMID 33457428, 2020). "High levels of tumor infiltrating activated CD4+ CD69+ T cells are associated with better locoregional control and improved survival in Head and Neck Squamous Cell Carcinoma patients." (PMID 33211709, 2020). "In patients with head and neck squamous cell carcinoma, highly suppressive CD4+CD39+GARP+LAP+ Tregs were expanded following chemoradiation therapy." (PMID 26885615, 2016). "While a rich T cell (CD3+) infiltrate correlates, per se, positively with a longer survival in several cancers, concurrent enrichment in CD8+ plus CD4+ T cells seems to be required for a better prognosis in some cancers, including head and neck squamous cell carcinomas (HNSCCs)." (PMID 38891095, 2024). "Similarly, a high level of cDC2s is strongly associated with longer progression-free survival and higher infiltration of CD4 T cells in both melanoma and human head and neck squamous cell carcinoma (HNSCC)." (PMID 36244976, 2022). "Furthermore, alterations in the PI3K pathway in head and neck squamous cell carcinoma (HNSCC) have been associated with a high density of cytotoxic cells, including central memory CD8+ T and memory CD4+ T cells, which are crucial for immunotherapy and anti-tumor immunity." (PMID 39544292, 2024). "MYL1, MYL2, and MYL3 were shown to have a positive correlation between expression levels and the infiltration of CD4+T cells in head and neck squamous cell carcinoma (HNSCC)." (PMID 39768172, 2024). "Studies in head and neck squamous cell carcinoma (HNSCC) patients reveal that infiltration of CD4+ and CD8+ T cells correlates with prognosis." (PMID 34239993, 2021). "Recent studies have found that YTHDC2 is associated with the level of immune infiltration of B cells, CD8+T cells, CD4+T cells, neutrophils and dendritic cells in head and neck squamous cell carcinoma (HNSCC)." (PMID 33777035, 2021).
head and neck squamous cell carcinoma (continued). "In head and neck squamous cell carcinoma (HNSCC), tumor endothelial cells release extracellular vesicles enriched in TGF-β1, inducing differentiation of naïve CD4+ T cells into Tregs and reinforcing immune suppression." (PMID 41394821, 2025). "Similar findings in a previous study revealed that downregulated MYH7 is a biomarker for the poor prognosis of head and neck squamous cell carcinoma (HNSCC), and that MYH7 promotes CD4+ T cell activation in cancer." (PMID 40709170, 2025). "Identification of HPV-16 E6-specific CD4+ and CD8+ T cell responses from TILs of head and neck squamous cell carcinoma." (PMID 36512410, 2023). "In head and neck squamous cell carcinoma, the group with high activated CD4(+)CD69(+) T cells had a better prognosis than the group with low CD4(+)CD69(+) T cells." (PMID 37033978, 2023). "In contrast, anti-CD73 Abs significantly downregulated the expression of PD-1 and CTLA-4 by CD4+ and CD8+ T cells in a murine transgenic head and neck squamous cell carcinoma (HNSCC) model, resulting in substantial reduction of tumor growth." (PMID 35711418, 2022). "Concerning head and neck squamous cell carcinomas (HNSCCs), previous studies have reported findings for a wide spectrum of T cell subsets such as CD8+ cytotoxic T cells, CD4+ T helper cells, and FoxP3+ regulatory T cells." (PMID 35741089, 2022). "Through upregulation of CD95L/FasL, peripheral blood CD4 Tregs were also able to trigger apoptotic CD95/Fas-dependent death of autologous CD8+ Т effectors in a co-culture system, as was demonstrated in head and neck squamous cell carcinoma." (PMID 29075318, 2017). "In addition, HPV in head and neck squamous cell carcinoma (HNSCC) tumor tissues was also associated with the infiltration of a variety of immune cells, including IL‐17+ CD8+ T lymphocytes, IFN‐γ+ CD8+ T lymphocytes, naive CD4+ T lymphocytes, and myeloid DCs." (PMID 41574027, 2026). "In head and neck squamous cell carcinoma, curcumin restored the cytotoxic function of effector T cells by modulating the expression of PD-1 and TIM-3 on CD4+or CD8+ T cells and CD4+CD25+Foxp3+ Tregs, promoting the expression of IFN-γ and granzyme B to exert its anticancer effects." (PMID 41458964, 2025). "Silencing of CMTM6 in head and neck squamous cell carcinoma (HNSCC) reduces β-catenin expression, inhibits stem cell properties, suppresses epithelial-to-mesenchymal transition (EMT) and cell proliferation, and promotes CD8+ and CD4+ t-cell infiltration." (PMID 36698778, 2022). "In head and neck squamous cell carcinoma (HNSCC), METTL3 and HNRNPC were highly expressed in tumor tissue than normal tissue, high expression of METTL3 and HNRNPC were positively associated with the infiltration of CD4 naive T cells, CD4 memory-activated T cells, and eosinophils." (PMID 35296338, 2022). "In head and neck squamous cell carcinoma (HNSCC), CD25high cells were enriched and represented 3% of CD3+CD4+ TILs compared to circulating CD3+CD4+ T cells of the same patients, which comprised 1% of CD3+CD4+ cells; circulating CD3+CD4+ T cells of normal controls comprised 0.4% of CD3+CD4+ cells." (PMID 25961057, 2015). "Among them, in head and neck squamous cell carcinoma (HNSCC), downregulation of CMTM6 not only decreases PD-L1 expression but also promotes infiltration of CD4+ and CD8+ T cells." (PMID 36698778, 2022). "In this systematic review and meta-analysis, we investigated the prognostic role of CD4+ and CD8+ TILs in head and neck squamous cell carcinoma (HNSCC)." (PMID 33668519, 2021). "Several studies have investigated the prognostic value of CD4+ and CD8+ T-cell TILs in head and neck squamous cell carcinoma (HNSCC)." (PMID 33668519, 2021). "The expression of BACH1 in Head and Neck squamous cell carcinoma (HNSC) has positive correlation to the infiltration of CD8+ T cells, B cells, neutrophils, macrophages, and myeloid dendritic cells, but no relative infiltration of CD4+ T cells." (PMID 35651942, 2022).
histoplasmosis (66 papers, 2007 to 2025). A disease caused by the fungus Histoplasma capsulatum. "Persons with HIV, especially those with CD4 counts below 150 cells/μL, are at heightened risk for severe forms of histoplasmosis, often leading to disseminated disease." (PMID 40137234, 2025). "HIV patients in Latin America have a greater risk of histoplasmosis than TB when CD4 counts are extremely low." (PMID 40137234, 2025). "The risk factors for Probable/Histoplasmosis were pancytopenia, < 50 CD4 + cells/μL and high AST levels." (PMID 34384448, 2021). "The risk factors for histoplasmosis were pancytopenia (OR 4.1, 95 CI 1.6–10.3, P = 0.002), < 50 CD4 + cells/μL (OR 3.1, 95 CI 1.3–7.3, P = 0.006) and Aspartate transaminase (AST) levels > 46 IU/L (OR 3.2, 95 CI 1.3–8, P = 0.01)." (PMID 34384448, 2021). "Previous studies in the American middle west had shown the occupational and environmental risk factors of HIV-associated histoplasmosis and some variables such as CD4 count, and past medical history and treatments." (PMID 24498446, 2014). "The patients with the lowest CD4 counts were both at increased risk of histoplasmosis and death within six months for patients with histoplasmosis." (PMID 24498446, 2014). "Our previous work showed that Tc1 immunity in CD4+ T cell deficient hosts was pivotal for vaccine-induced resistance against blastomycosis and histoplasmosis." (PMID 22829762, 2012). "The logistic regression analysis showed that the risk factors for histoplasmosis were pancytopenia (OR 4.1, 95% CI 1.6–10.3, P = 0.002), < 50 CD4 + cells/μL (OR 3.1, 95% CI 1.3–7.3, P = 0.006) and Aspartate transaminase (AST) levels > 46 IU/L (OR 3.2, 95% CI 1.3–8, P = 0.010)." (PMID 34384448, 2021). "In Latin America, histoplasmosis is often classified as the most common cause of death in patients with advanced HIV disease (defined as a cluster of differentiation-4 (CD4) T-cell count below 200 cells/mm3, or a WHO clinical stage 3 or 4 event at presentation for care." (PMID 34356955, 2021). "Severe histoplasmosis cases occurred almost exclusively in patients with CD4 counts of <200 cells/mm3 (median 31 cells/mm3; IQR, 3–231 cells/mm3)." (PMID 40235555, 2025). "Many countries have seen an increase in the number of histoplasmosis cases in advanced HIV patients since access to antigen testing through screening of people with CD4+ T-lymphocytes < 200 cells/μL." (PMID 40137234, 2025). "In 9% of cases (3/32), the diagnosis of histoplasmosis led to the identification of idiopathic CD4+ T lymphopenia." (PMID 40558973, 2025). "the percentage of patients who had a CD4 lymphocyte count of <150 cells/mL is even higher (94.7%), confirming the preferential presentation of histoplasmosis in severely immunocompromised patients." (PMID 38993488, 2024). "An intriguing observation was made in a case of cutaneous histoplasmosis, where a patient initially presented with transient depletion of CD4+ T lymphocytes, with a count of 161 cells/μL." (PMID 38883060, 2024). "Nevertheless, there is a possibility that we were dealing with a case of idiopathic CD4+ T lymphocytopenia, as there are several reports of patients presenting with histoplasmosis as the initial manifestation." (PMID 38883060, 2024). "In patients with CD4 counts <100/μL, itraconazole significantly reduced cases of histoplasmosis 7/103 (7%) for placebo recipients versus 2/101 (2.0%) in those receiving itraconazole." (PMID 36730157, 2023). "En el primer paciente, su estado de inmunosupresión grave por la infección con HIV, con un recuento de 274 linfocitos CD4+ por μl, permitió la colonización oportunista de H. capsulatum y desarrolló histoplasmosis diseminada con manifestaciones cutáneas." (PMID 37721919, 2023). "The Infectious Diseases Society of America has recommended primary prophylaxis for persons with CD4 counts <150/mm3 when the annual incidence of histoplasmosis exceeded 10 per 100 person-years." (PMID 36730157, 2023).
histoplasmosis (continued). "Urine test for histoplasmosis antigen is indicated in patients with CD4 count < 100 cells/μL in areas where histoplasmosis is endemic, and it must be repeated every year." (PMID 37294504, 2023). "It should be emphasized that all these studies used urine samples from patients with advanced HIV disease, having a CD4+ cell count under 100 cell/mm3 and proven histoplasmosis." (PMID 39184036, 2022). "In people living with HIV and CD4 cell counts < 150 cells/mm3 prophylaxis with itraconazole is recommended in specific areas of endemicity where the incidence of histoplasmosis is 110 cases per 100 patient-years." (PMID 36104715, 2022). "In patients who had a CD4 cell count ≥ 350 cells/mm3, TB was more frequent than histoplasmosis (2.9% vs. 1.1%, p = 0.0807)." (PMID 33916153, 2021). "The difference between histoplasmosis and TB incidence was statistically significant in patients with CD4 cell counts <50 cells/mm3 (19.7% vs. 11.5%, p = 0.003)." (PMID 33916153, 2021). "It became clear that there is an inversely proportional relationship between the CD4 + cell count and the incidence of histoplasmosis." (PMID 34384448, 2021). "IDSA and NIH/CDC guidelines recommend consideration of prophylaxis during a histoplasmosis outbreak or in settings in which the disease incidence is >10 cases per 100 patient-years for persons with CD4 <150/μL." (PMID 34071599, 2021). "Histoplasmosis was the most common OI with an overall incidence of 7.9% rising to 19.7% in patients with CD4 cell counts < 50 cells/mm3." (PMID 33916153, 2021). "We present a case of a 60-year-old man who was diagnosed with disseminated histoplasmosis involving soft palate, duodenum, colon and bone marrow in the setting of idiopathic CD4 T-lymphocytopenia." (PMID 34938625, 2021). "Histoplasmosis was the most frequent OI (7.9%), followed by TB (7.1%); 94.4% of these infections occurred in patients with a CD4 < 350 cells/mm3." (PMID 33916153, 2021). "Disseminated histoplasmosis (DH) was estimated to occur at an annual rate of 1.5% in HIV patients with CD4 counts <200 × 106/mL, which means that ~1800 patients probably have this life-threatening, and probably fatal, infection each year." (PMID 29601494, 2018). "The median CD4+ T cell count among individuals with histoplasmosis was 33 cells/mL (IQR 10–59), lower than HIV individuals with a different IFI, but not statistically significant (38 cells/mL, IQR 10–59, p = 0.84)." (PMID 30205586, 2018). "Existing data demonstrates that in HIV-infected patients with histoplasmosis, the disease is disseminated in 95% of the cases, and in 90% of the cases it occurs in patients with CD4 counts below 200/mm3." (PMID 29742119, 2018). "Prophylaxis with itraconazole is recommended in patients with HIV and CD4 cell counts <150 cells/mm3 in specific areas where the incidence of histoplasmosis is >10 cases per patient-years." (PMID 27812393, 2016). "Patients with both CD4 counts <50 per mm3 and CD8 counts under 643 had the highest risk of histoplasmosis." (PMID 24498446, 2014). "Among the well-described cases, most involved patients with poor immunologic status (mean CD4 count 55/mm3), which also occurs with histoplasmosis due to variety capsulatum." (PMID 18217546, 2007). "After adjustments, a lower initial CD4 count, a higher initial HIV viral load, and residing in French Guiana or in the French Antilles (Guadeloupe/Martinique) were associated with higher hazard ratios of histoplasmosis." (PMID 40562731, 2025). "The histoplasmosis prevalence among participants with a CD4 < 100 cells/mcL was 2.5% (4/158)." (PMID 37504745, 2023). "Hence, after adjusting for age, sex, and CD4 counts, HAART was associated with an 80% reduction of histoplasmosis incidence (adjusted HR = 0.2 (0.1 to 0.4), P < 0.001)." (PMID 36730157, 2023). "In our study, 92% of the histoplasmosis cases occurred in patients with <350 CD4 cells." (PMID 34946197, 2021).
histoplasmosis (continued). "Among patients with histoplasmosis, 58/87 (67%) presented with counts <50 CD4 cells per μl." (PMID 34536307, 2021). "In this series, the HIV patients with disseminated histoplasmosis (i.e., more than one infection site) had a CD4 count of <200 cells/mm3, extracellular H. capsulatum, >50 yeasts per hot spot, and either cluster pattern II (cluster or chain of >5 yeasts) or III (rosette > 10 yeasts)." (PMID 34356955, 2021). "With the arrival of new Histoplasma antigen detection methods, the possibility of screening for histoplasma, analogous to screening for cryptococcus, raises a new and important research question: should we screen all patients with less than 200 CD4 for histoplasmosis?" (PMID 32706836, 2020). "Hence, HIV-infected patients with disseminated histoplasmosis usually have CD4 counts under 200 per mm3 and mostly under 50 per mm3." (PMID 33194840, 2020). "In conclusion, immunological factors such as low CD4 count, low CD8 count, low CD4 counts at the Nadir, the absence of antiretroviral treatment and/or oral fluconazole, and male gender were associated with an increased risk of histoplasmosis." (PMID 24498446, 2014). "Importantly, as the CD4 count decreases, the likelihood of histoplasmosis rather than TB being the cause of illness rises in areas with high rates of histoplasmosis infections." (PMID 40137234, 2025). "Furthermore, in those with histoplasmosis, HAART was also associated with a significant reduction of death at 6 months (adjusted HR = 0.2 (0.0 to 0.5), P = 0.003) after adjusting for age, sex, CD4, and CD8 counts." (PMID 36730157, 2023). "Histoplasmosis has thus become a major opportunistic infection in patients with advanced HIV infection in endemic areas, where it has often been ranked as the most common AIDS-defining infection and cause of death for patients with CD4 cell counts <200 cells/mm3." (PMID 33194840, 2020). "However, if the CD4 count is >200 cells/mm3, a diagnosis of histoplasmosis is unlikely." (PMID 31847076, 2019). "Hence, HIV-associated histoplasmosis (HAH) is a common AIDS-defining condition in endemic areas for Histoplasma capsulatum, with the highest incidence among people living with HIV with a CD4 count <150 cells/mm3." (PMID 31847076, 2019). "Regarding the immunovirological status at the diagnosis of histoplasmosis, the median HIV-1 viremia, available for 55 patients, was 199,526 copies/ml [IQR 38690–750,000]; CD4 T-cell absolute count was available for 106 PLWH and was <200 cells/uL in all cases." (PMID 38993488, 2024). "TB and histoplasmosis are frequently discovered in advanced HIV patients, particularly when CD4+ cell counts are less than 50 cells/μL." (PMID 37729126, 2023). "In an exploratory way, having < 200 CD4 + cells/μL showed the highest sensitivity and a high NPV (> 90%) for the diagnosis of histoplasmosis." (PMID 34384448, 2021). "The low levels of CD4 cells and the high HIV-1 viral load observed in our cases, and in other autopsy cohort highlight the elevated fatality rate of histoplasmosis in patients with advanced HIV disease in the endemic areas in Brazil." (PMID 33819269, 2021). "Immunological status seems to be fundamental in histoplasmosis manifestation: in our systematic review, of the 106 patients with reported CD4 levels at the time of histoplasmosis diagnosis, none had CD4 levels above 200 cells/ml." (PMID 38993488, 2024). "A pesar de que el 90 % de los pacientes con histoplasmosis cutánea y el 100 % de aquellos con criptococosis cutánea tenían recuentos de CD4 menores de 100 células/mm3, no se encontró una relación estadísticamente significativa con dicho valor." (PMID 35867921, 2022). "In the subset of patients with CD4 counts <100/μL, itraconazole significantly reduced cases of histoplasmosis and cryptococcosis but did not improve survival." (PMID 34071599, 2021).